ATG5 (autophagy related 5)
Diseases named in the same sentence as ATG5 in open-access papers (continued):
Sharing a sentence is not in itself a finding about the gene and the disease.
tumor (continued). "Tumor suppressive roles for autophagy were demonstrated in mice with Becn1/Beclin-1 heterozygosity, systemic mosaic Atg5 deletion or liver-specific deletion of Atg7." (PMID 26956429, 2016). "Tumor incidence 4 weeks after injection was significantly (p < 0.05) higher in control diet-fed mice with Atg5+/+ tumors (12/14, 86 %) than Atg5−/− tumors (5/14; 36 %)." (PMID 27651895, 2016). "Final tumor volume was greatest for Atg5+/+ tumors in control-fed mice, intermediate for Atg5+/+ tumors in CR-fed mice and Atg5−/− tumors in control-fed mice, and lowest for Atg5−/− tumors in CR mice." (PMID 27651895, 2016). "One study reported that over-expression of Atg5 made the tumor cells sensitive to chemotherapy, while silencing the Atg5 gene with short interfering RNA made the cells partially resistant to chemotherapy." (PMID 26950124, 2016). "Knock down of Beclin1 or ATG5 or eIF2α expression significantly reduced the ability of [sorafenib + sildenafil + afatinib] treatment to kill tumor cells." (PMID 27259258, 2016). "Tumor growth and final tumor volume was greatest for Atg5+/+tumors in control-fed mice, intermediate for Atg5+/+tumors in CR-fed mice and Atg5−/− tumors in control-fed mice, and lowest for Atg5−/− tumors in CR mice." (PMID 27651895, 2016). "Genetic deletion of the autophagy protein ATG5 results in impaired progression of KRas(G12D)-driven lung cancer and promotes the survival of tumor bearing mice." (PMID 25617802, 2015). "High level of Atg5 expression were observed in the tumor tissues treated with dl/shMet4+5, whereas the expression of Atg5 was very minimal in the tumor tissues treated with PBS or dl/LacZ." (PMID 25726528, 2015). "Next to determine the mechanistic role of autophagy in tumor growth inhibition; immunohistochemical study was conducted using autophagy-specific Atg5, which is required for the elongation of autophagosomes." (PMID 25726528, 2015). "Particularly convincing evidence for the tumor-suppressive role of autophagy is the development of multiple liver adenomas in mice with a deletion of Atg5 and Atg7." (PMID 26561802, 2015). "Enforced Atg5 expression sensitizes tumor cells to chemotherapy in vitro and in vivo while Atg5 silencing results in chemotherapeutic resistance." (PMID 25481044, 2014). "Enforced expression of ATG-5 sensitized tumor cells to anticancer drug treatment both in vitro and in vivo; in contrast siRNA-mediated inhibition of ATG-5 led to partial resistance to chemotherapy." (PMID 25329677, 2014). "DEF was 4.5 for ATG5KD tumours and 3.7 for BECN-1KD tumours, revealing ATG5 or BECN-1 depletion sensitized A549 tumours to IR." (PMID 24037090, 2014). "All 26 tumor samples with deletions of the ATG5 locus as verified by FISH and the remaining 35 samples with deletion signals below the cut-off level were then analyzed by qPCR." (PMID 24733537, 2014). "We found that AGD was 4, 49 and 39 days for control (SCR), ATG5-deficient (ATG5KD) and BECN-1-deficient (BECN-1KD) tumours, respectively." (PMID 24037090, 2014). "Targeting SDE2 restores ATG5-dependent autophagy, activates ferroptosis, and inhibits tumor growth." (PMID 41666676, 2026). "ATG5-mediated autophagy eliminates damaged organelles and misfolded proteins, preventing cellular stress and genomic instability, both of which contribute to tumor development." (PMID 39874138, 2025). "In several in vitro and in vivo CRC settings, the miRNA-mediated knock-down of autophagy was associated with increased resistance to therapy, tumor growth, invasiveness, metastasization, and poor prognosis, such as was the case with MiR-338-5p silencing of PI3KC3 and miR-183-5p silencing of ATG5." (PMID 40722631, 2025). "This process may occur via the acetylation of PAK1 (p21-activated kinase 1), which leads to autophagy and tumor proliferation by phosphorylating ATG5, thereby protecting ATG5 from ubiquitination-dependent degradation." (PMID 41294712, 2025).
tumor (continued). "However, in this same Apc+/− CRC model, the heterozygous deletion of ATG5 led to an increased tumor burden." (PMID 40722631, 2025). "Interestingly, similar to BECN1 knockdown, ATG5 silencing also reversed the autophagy-promoting and tumor-suppressive effects of DHX9 silencing." (PMID 40659605, 2025). "Similarly, treatment with the ferroptosis activator (Erastin) not only suppressed tumor volume but also decreased the expression of autophagy-related proteins (ATG5, ATG7, and BECN1), along with increased cell apoptosis." (PMID 41502518, 2025). "Furthermore, we established an in vivo model system to validate CELF1’s regulatory role on ATG5-mediated autophagy as a tumor-suppressive mechanism." (PMID 40781108, 2025). "The released Mn2+ ions catalyzed the Fenton reaction, generating hydroxyl radicals (•OH) to induce oxidative damage, while the ATG5 DNAzyme specifically cleaved ATG5 mRNA, effectively inhibiting autophagy and preventing tumor cells from resisting CDT‐induced oxidative stress." (PMID 40529859, 2025). "Moreover, in human cancers, mutations in autophagy-related genes such as ATG2, ATG5, ATG9, and ATG12 have been observed in colorectal and gastric cancer, implying a tumor-suppressive role for autophagy." (PMID 40214497, 2025). "Indeed, our in vivo study revealed notable differences in efficacy, where treatment with ATG5-knockout CAR-T cells elicited an immediate reduction in tumor growth, followed by rapid tumor clearance and complete remission in all mice." (PMID 41279553, 2025). "We isolated the tumours and performed IHC analysis using ATG5, GPX4, NLRP3, and Ki-67 staining." (PMID 38499622, 2024). "In addition to AMPK, LC3 and ATG5 have been confirmed to be involved in the propofol-induced regulation of autophagy in tumor cells." (PMID 38482052, 2024). "In contrast, Atg5 shifts to a pro‐tumor status under autophagy deprivation conditions." (PMID 38826147, 2024). "Furthermore, Atg5 has been shown to be a tumor suppressor in various cancers under normal autophagy conditions." (PMID 38826147, 2024). "Our data demonstrated that autophagosome formation and MM cell killing by the drug combination was most effectively reduced by knocking down the expression of ULK1, Beclin1 or ATG5, strongly arguing that macroautophagy played a key role in tumor cell execution." (PMID 38441437, 2024). "However, subcutaneous inoculation of Atg5‐overexpressed Atg7−/− MEF cells into NOD/SCID mice induced temporary tumor formation in the early stage of tumor formation." (PMID 38826147, 2024). "In summary, Atg5 functions as a tumor suppressor to protect the cell under normal conditions." (PMID 38826147, 2024). "Intriguingly, overexpression of Atg5 in autophagy‐deficient Atg7−/− MEF stable clones significantly increased cell proliferation, colony formation, and cell migration in vitro, and transiently promoted tumor formation in vivo." (PMID 38826147, 2024). "OPN overexpression could promote GPX4 level and decrease autophagy-related LC3II/I, Atg5 and Atg7 expressions in tumor cells, which was subsequently reversed by LY294002 administration." (PMID 38526702, 2024). "Tumor ATG5 expression was lower than that in benign nevi and normal skin cells." (PMID 39371094, 2024). "Similarly, increasing ATG5 levels in cultivated tumor cells prevent their growth and lead to senescence." (PMID 39371094, 2024). "Calycosin regulated MUC1, Atg5 protein expression snail protein, G1 phase arrest, and TGF‐β in MIA‐PaCa2 cell line at 50–100 μM, leading to cause apoptosis and autophagy, while at 30 mg/kg prevent tumor growth in C57/BL6 mice." (PMID 38230908, 2024). "Compared with that of PC-3 + PBS or PC-3 + NFs groups, CAFs could elevate tumor size, volume and weight, suggesting that CAFs accelerated xenograft tumor growth; whereas knockdown of ATG5 abrogated CAFs’ effects on tumor growth." (PMID 37000314, 2023).
tumor (continued). "Moreover, CAFs transfected with si-ATG5 were also employed to mix with PC-3 cells for illuminating the function of ATG5 in CAFs’ effects on tumor growth." (PMID 37000314, 2023). "In vitro studies have confirmed the observed in vivo, reduced expression of ATG5 compared to its expression in normal colonic cell lines, suggesting that ATG5 may function as a tumor suppressor." (PMID 36835075, 2023). "Depletion of ATG5 in CAFs inhibited the xenograft tumor growth and lung metastasis of PCa cells." (PMID 37000314, 2023). "Taken together, depletion of ATG5 in CAFs repressed PCa tumor growth." (PMID 37000314, 2023). "Interestingly systemic Atg5 depletion also promoted the infiltration of cytotoxic T cells toward tumors, enhancing the anti-tumor effect and increasing the survival rate of these lung tumor-harboring mice." (PMID 38067169, 2023). "Furthermore, knockout of both Atg3 and Atg5 resulted in increased IL-9 production in Th9 cells leading to improved tumor control, whereas autophagy activation suppresses their differentiation by selectively degrading Th9 cell transcription factor PU.1." (PMID 38071322, 2023). "Therefore, genetic ablation of Atg5 can increase the metabolic activity and tumor-killing ability of CAR T cells." (PMID 37675121, 2023). "Moreover, this research demonstrated that CAFs promoted malignant phenotypes and tumor growth of PCa via ATG5." (PMID 37000314, 2023). "In addition, dietary glutamine supplementation, mimicking attenuated autophagy, retarded tumor expansion in Atg5+/+ mice." (PMID 35966597, 2022). "Furthermore, comparing to the Atg5+/+ mice fed with control diet, tumor glutamine level was elevated in the Atg5+/+ mice fed with high glutamine diet." (PMID 35966597, 2022). "At this point, continued growth was noted only in tumor-bearing Atg5+/+ mice." (PMID 35966597, 2022). "A recent study suggested that ATG5 acts as a tumor promoter in CRC metastasis and drug resistance." (PMID 36333388, 2022). "Indeed, IL-6 or IL-8 increased ATG5/12 conjugation and decreased p62, indicating cytokine-induced autophagy and, most importantly, autophagy inhibition suppressed tumor growth." (PMID 35884904, 2022). "However, we observed a very modest, if any, effect on tumor burden in Atg5+/+ mice by this anti-CD25 monoclonal antibody." (PMID 35966597, 2022). "Based on our observations of a marked infiltration of inflammatory cells, including macrophages and leukocytes in inducible MSTs 41 and elevated proinflammatory cytokines in naïve Atg5flox/flox mice, we first analyzed and compared leukocytes between tumor-bearing Atg5+/+ and Atg5flox/flox mice." (PMID 35966597, 2022). "Furthermore, they found that knockdown of Atg5 significantly inhibits tumor growth and metastasis in vitro." (PMID 35715752, 2022). "To determine whether tumoral autophagy can influence bone components of the tumor microenvironment, we next compared the effect of WT or Atg5 KO tumor cells on OC differentiation in vitro." (PMID 40396018, 2022). "Notably, both glutamine and its metabolite α-ketoglutarate (αKG) levels were higher in SMGs from tumor-bearing Atg5flox/flox mice at Day 14 comparing to tumor-bearing Atg5+/+ mice." (PMID 35966597, 2022). "For instance, ATG5 is considered a contributor for inducing ferroptosis, and its high expression promotes tumor metastasis; BAP1 encodes a nuclear deubiquitinating enzyme, which plays an important role in ferroptosis and tumor suppression." (PMID 35042463, 2022). "Consequently, inhibition of autophagy with the use of chroloquine or with shRNA against atg5 suppresses their growth in vitro and attenuates tumor development in pancreatic cancer mouse models." (PMID 36505808, 2022). "Thus, ATG5-/- CD8+T cells gained an effector memory state that promoted CD8+ T cell-mediated tumor rejection and INF-γ release." (PMID 36300110, 2022).
tumor (continued). "After a 3-day coculture with Atg5 KO tumor cells, we observed a 50% increase in the number of tartrate-resistant alkaline phosphatase positive multinucleated cells, suggesting that the presence of Atg5 KO tumor cells stimulates osteoclastogenesis." (PMID 40396018, 2022). "The results demonstrated that ATG5 expression was significantly positively correlated with tumor proliferation signatures, MYC targets, DNA repair, DNA replication, and G2M checkpoint in HNSCC (p < 0.05), and the Spearman coefficients were 0.38, 0.28, 0.25, 0.34, and 0.41, respectively." (PMID 36185455, 2022). "The autophagy in PCa induced by CHRM1 was summarized with a model, which activates the AMPK/mTOR pathway by linking the Gq protein, acts on Atg5 and other autophagy-related genes, and induces autophagy, thereby enhancing the migration and invasion ability of tumor cells." (PMID 35720225, 2022). "Furthermore, an important kinase, PRKCA/PKCα, that regulates hypoxia-mediated autophagy via ATG5 and Beclin1, stimulates tumor-initiating cell renewal in CRC." (PMID 36160153, 2022). "Interestingly, it has been indicated that ATG5 or ATG7 deletion in T cells produces severe tumor implant rejection in the syngeneic mouse tumor model." (PMID 36160153, 2022). "Accordingly, ATG5-silence mediate autophagy suppression could enhance effect of anti-tumor therapy on advanced solid cancer." (PMID 34253689, 2021). "The inhibition of hsa-miR-30a may retard tumor progression by decreasing Beclin-1 and ATG5 expression and inhibiting autophagy, thereby sensitizing the tumor cells to the drug therapy." (PMID 34203465, 2021). "Besides, another Pan-cancer analysis explored the role of ATG5 in tumor metabolism and tumor immunity." (PMID 34222028, 2021). "Moreover, BO downregulated the expressions of beclin-1, as well as several mRNA levels of autophagy-related genes (Beclin1, Atg5 and Lc3), suggesting that the inhibition on autophagy plays a critical role in tumor suppression by BO." (PMID 34658867, 2021). "In tumours, the status of several autophagy proteins, such as LC3b, ATG5, Beclin1 and its interacting proteins high mobility group Box 1 (HMGB1) and the Bcl-2-family, mostly assessed using immunohistochemistry, has been evaluated as a marker in several tumour types." (PMID 32929194, 2021). "Previous studies showed that miR-567 could regulate KPNA4, ATG5 and then inhibited tumor progression or chemoresistance." (PMID 34226531, 2021). "In CRC, ATG5 depletion can either inhibit or promote tumor growth." (PMID 33926066, 2021). "Herein, our results showed that high ATG5 protein levels might facilitate tumor progression and survival, which, in turn, might result in worse overall survival and recurrence." (PMID 33926066, 2021). "Beclin-1, Atg4, Atg5, and Atg7 have indicated a tumor-suppressive function." (PMID 34122670, 2021). "The expression of ATG5 was initially verified with IHC staining in tumor tissues of CRC patients." (PMID 33926066, 2021). "However, the ATG5 mRNA level was decreased in the tumor compared with that found in the normal tissues." (PMID 31959887, 2020). "Therefore, CDKL3 played a pivotal role in promoting tumor progression by ATG5 activation, which is a crucial gene involved in autophagy regulation." (PMID 32974198, 2020). "This tumour-suppressive role of autophagy is supported by early studies that showed increased development of spontaneous, potentially benign, lung and liver tumours and lymphomas in mice deleted of autophagy genes Beclin 1, Atg7 and Atg5." (PMID 32873152, 2020). "Dysfunction in autophagic elements such as ATG12, ATG9B, ATG4 and ATG5 may result in tumor initiation." (PMID 32426106, 2020). "The expression of autophagy-related genes light chain 3 (LC3), Beclin-1, ATG5 and p62 could be used as indicators of tumor recurrence and poor prognosis." (PMID 33004943, 2020).
tumor (continued). "Moreover, the deletion of Atg5 or Atg7, atg13 or Ulk1, Fip200, and Atg7 decrease tumor progression in various oncogene-driven cancer types." (PMID 33260729, 2020). "In addition, CAP significantly increased the mRNA expression of LC3 and ATG5 in B16 tumor cells in comparison to untreated control cells." (PMID 32650505, 2020). "For instance, a reversible model of Atg5 deletion showed that while Atg5 deficient mice (ATG5i) exhibited tissue inflammation and degeneration, eventually succumbing to these phenotypes, there was no sign of overt tumor development." (PMID 33381037, 2020). "Importantly, although homozygous deletion of Atg5 inhibited tumor formation in a murine model of pancreatic carcinogenesis, heterozygous deletion or incomplete knockdown led to increased tumor formation and metastasis." (PMID 32344698, 2020). "For example, targeting the gene for the autophagy related 5 (ATG5) protein that stimulates in vivo metastasis through EV production might have promising results in holding tumor progression." (PMID 33202771, 2020). "Mechanistic detection demonstrated that CDKL3 might promote tumor profession, invasion, metastasis, and prohibit tumor apoptosis partly by ATG5 activation." (PMID 32974198, 2020). "More recently, we have shown that neratinib is capable of inducing LC3-associated phagocytosis (LAP), which requires expression of the protein Rubicon; knock down of Rubicon was significantly more protective than knock down of Beclin1 or ATG5 at preventing tumor cell killing." (PMID 31380285, 2019). "Taken together, our results indicated that HIF1α could promote tumor cell proliferation in vivo by promoting ATG5 expression and autophagy levels." (PMID 31700698, 2019). "Similarly, autophagy inhibition with shRNA targeting ATG5 or small molecule inhibitors leads to tumor regression and longer survival in pancreatic cancel xenografts and mouse models." (PMID 31905604, 2019). "Instead, EC-specific Atg5 deletion even enhanced the aberrant tumor vasculature." (PMID 30949450, 2019). "Moreover, upregulation of IDH1-AS1 facilitated PCa tumor growth by posttranscriptionally regulating ATG5 expression." (PMID 31570703, 2019). "Intriguingly, overexpression of HIF1α by HIF1α-M could increase tumor size and the effect could be abolished by knockdown ATG5 by si-ATG5 in BALB/cA-nu/nu nude mice." (PMID 31700698, 2019). "HIF1α promotes tumor cell proliferation in vivo by promoting ATG5 expression and autophagy levels." (PMID 31700698, 2019). "Moreover, we examined the transcription levels in harvested tumor xenograft samples, and results showed that the mRNA levels of HIF1α and ATG5 were notably upregulated in HIF1α-overexpressed group." (PMID 31700698, 2019). "Interestingly, QNZ enhanced activation of the CHOP pathway inTC-1 tumor cells and Atg5+/+ and Atg5−/− MEF cells." (PMID 28904818, 2017). "To investigate whether the effect of the ATG5 SNPs on the prognosis of patients was mediated by modulating the expression of ATG5, we analyzed the expression levels of ATG5 in tumor and adjacent normal tissues from patients with early-stage ESCC by IHC." (PMID 29207660, 2017). "Moreover, higher levels of ATG5 expression in both normal and tumor tissues exhibited a trend to correlate with poor prognosis of patients." (PMID 29207660, 2017). "Therefore, knockdown of ATG5 and chloroquine treatment sensitize tumor cells to camptothecin and to camptothecin-related compounds." (PMID 29383142, 2017). "After replication of oncolytic adenoviruses, Atg5 is upregulated in infected tumor cells." (PMID 28698504, 2017).